EZH2 (enhancer of zeste 2 polycomb repressive complex 2 subunit)
Diseases named in the same sentence as EZH2 in open-access papers (continued):
Sharing a sentence is not in itself a finding about the gene and the disease.
cancer (continued). "Although overexpression of EZH2, a catalytic subunit of the polycomb repressive complex 2 (PRC2), is an eminent feature of various cancers, the regulation of its abundance and function remains insufficiently understood." (PMID 33849069, 2021). "Instead, this study showed that both EZH2-mediated H3K27me3 modification and DNMT1-mediated DNA methylation suppressed the expression of CXCL9 and CXCL10 in cancer cells." (PMID 33403469, 2021). "Growing evidence suggests a synergistic anti‐cancer action of the combination of EZH2 and HDAC inhibition in several cancers." (PMID 34213777, 2021). "Different EZH2 inhibitors, such as tazemetostat and CPI-1205, are currently being evaluated in clinical trials in multiple cancer types." (PMID 34680389, 2021). "Since IFNγ strongly induces NLRC5 gene expression, further studies in normal and cancer cells are needed to resolve the conundrum of STAT1-mediated gene activation and EZH2-mediated epigenetic repression of the same target genes." (PMID 33671123, 2021). "We identified a novel cancer driver lncRNA, PRADX that recruits PRC2/DDX5 complex by interacting with EZH2 and promotes NF-κB activity via UBXN1 suppression, which in turn contributes to GBM and COAD tumorigenesis." (PMID 33754075, 2021). "Therefore, EZH2 might be a promising target for cancer therapy." (PMID 33966039, 2021). "Furthermore, EZH2 may be involved in preserving the stemness of cancer stem cells." (PMID 34737746, 2021). "EZH2 and LSD1, which are enriched in various cancers, have been well‐recognized for their involvement in the epigenetic regulation." (PMID 33145887, 2021). "The link between the modification of BCL2’s chromatin architecture and its constitutive activation in estrogen-resistant cancer cells has been demonstrated, identifying JMJD3 and methyltransferase EZH2 as interesting therapeutic targets." (PMID 33478063, 2021). "A series of HDMs inhibitors and HMT inhibitors involving LSD1 inhibitor SP-2577 (Seclidemstat) (NCT03895684), EZH2 inhibitor CPI-1205 (NCT03525795), Tazemetostat (NCT01897571) are in trials against multiple cancer types." (PMID 33996581, 2021). "Therapies targeting oncogenic deregulation of the epigenome, such as EZH2 and BET‐family inhibition, have been successfully used in clinical and preclinical trials for many diverse cancers, such as non‐Hodgkins lymphoma and glioblastoma." (PMID 34213777, 2021). "In contrast, treatment with SAHA alone reduced EZH2 levels in the MYCamp cells, consistent with the fact that SAHA triggers inhibition of cell cycle progression and increases apoptosis in cancer cells with this genetic context." (PMID 34262032, 2021). "SPARCS are located in the antisense of the 3′ untranslated regions of IFN-stimulated genes, and low levels of EZH2 trigger expression of these ERVs when exposed to IFN-γ, leading to innate immune signaling in cancer." (PMID 33436557, 2021). "Some selective inhibitors of specific protein methyltransferases, including DOT1L, EZH2 and PRMT5, are currently under clinical investigation as cancer therapeutics." (PMID 33778494, 2021). "Valemetostat is a dual inhibitor of EZH1 and EZH2 that prevents trimethylation of H3K27, leading to altered gene expression patterns, which suppresses proliferation of EZH1/2-dependent cancer cells." (PMID 34944658, 2021). "In nonsmall cell lung carcinoma, LINC01133 suppresses the transcription of KLF2, P21, and E‐cadherin by binding to EZH2 and LSD1, resulting in increased cancer cell growth and invasion." (PMID 34047479, 2021). "In breast cancer cells, an epigenetic factor, CDYL2, recruits EZH2 and G9a to repress expression of the tumor suppressive microRNA gene MIR124 and to promote cancer cell migration, invasion, and stemness." (PMID 33436557, 2021). "As such, several cancers with SWI/SNF subunit alterations have increased H3K27me3 and an increased sensitivity to EZH2 deletion." (PMID 34617019, 2021).
cancer (continued). "According to the results presented in this study, USP44 regulates enhancer of zeste homolog 2 (EZH2), a histone H3 lysine 27 methyltransferase, which is involved in the development and progression of various cancers." (PMID 34572834, 2021). "EZH2 inhibitor, GSK343, was shown to suppress stem-like state of cancer cells in glioma cells and to reverse EMT." (PMID 33572108, 2021). "The core of the study is to examine the certain relationship between EZH2 and SQLE, and the combined drug treatment has produced a certain anti-cancer effect." (PMID 33986254, 2021). "Intriguingly, mounting evidence has demonstrated the regulatory relationship between EZH2 and KLF2 in a variety of cancers." (PMID 34462420, 2021). "Enhancer of zeste homolog 2 (EZH2) is a highly conserved histone methyltransferase (HMTase) and is abnormally expressed in various cancers." (PMID 34869021, 2021). "Aberrant activation or expression of EZH2 are believed to drive a H3K27 methylation (H3K27me)-dependent cell growth, making EZH2 a promising target for cancer therapy." (PMID 33794893, 2021). "We show that EZH2 inhibitors induce ERVs, LINE-1, and an interferon response in a variety of cancer types." (PMID 34966479, 2021). "EZH2 and KDM6A / B play the opposite role in catalyzing the methylation of H3K27, but they can also exhibit cancer-promoting activity." (PMID 34001062, 2021). "EZH2-mediated histone methylation represses NLRC5 in stem cells and cancer cells, whereas IFNγ promotes the same events in macrophages on certain genes." (PMID 33671123, 2021). "Human methyltransferases, such EZH2, PRMT5, and DOT1L, are being actively pursued as drug targets for various cancers." (PMID 34285249, 2021). "On the other hand, EZH2, the methyltransferase component of PRC2, is upregulated in many cancer types, including HBV-related HCCs." (PMID 33614973, 2021). "EZH2 also interacts with noncoding RNAs, including lncRNA DLEU2 to sustain cccDNA transcription and transcription of cancer relevant genes." (PMID 33614973, 2021). "Over the past decades, multiple epigenetic regulators have been identified as modulators of the EMT program in various cancer cell lines in 2D, e.g., HDAC, DNMT, LSD1, KDM6B, PRMT5, EZH2, and G9a67–76." (PMID 34253738, 2021). "EZH2 binds to STAT3, which leads to enhanced STAT3 activity via the increased tyrosine phosphorylation of STAT3 in cancer stem cells (CSCs)." (PMID 33823894, 2021). "Three metabolic enzymes (EZH2, ENO2, and RRM2) were found to be commonly regulated by S-M, TF-M, and miR in all three cancers." (PMID 34790674, 2021). "Previous studies have shown that lncRNA ZFAS1 plays an oncogenic role by interacting with EZH2 in GC and is also upregulated in HNSCC because it is positively related to cancer initiation and metastasis." (PMID 34249125, 2021). "There exist a positive correlation between EZH2 and the five genes (CHEK1, MAD2L1, RFWD3, TRAIP, and TTK) in the majority of detailed cancer types as shown in the form of heatmap data." (PMID 34381492, 2021). "It has been reported EZH2 and 5-HT derived from peripheral TPH1 in cancer tissues independently contributes to cancer malignancy by stimulating cancer cell proliferation and invasion." (PMID 34771469, 2021). "Some histone modification regulators (e.g., EZH2 and LSD1) have been found to be aberrantly overexpressed in various malignant tumors." (PMID 34017344, 2021). "Next, we screened the downstream genes of EZH2 to explore which genes were regulated by EZH2 in the LSCC cell line TU-177 and Hep-2 carcinoma cells." (PMID 34257531, 2021). "Five TFs, SUZ12, SMAD4, REST, EZH2 and NFE2L2, were found to be enriched in all four cancers, suggesting that transcriptional dysregulation of tumors with aberrant AMPK signaling involved direct physical associations of these TFs with target DEGs." (PMID 32807122, 2020).
cancer (continued). "Our analyses focused on several key NMPs including SATB1/2, SAFB1/2, EZH2, SUZ12, BMI1, PCL3, RAE28, and CTCF, as these NMPs have been shown to be aberrantly expressed in cancers." (PMID 33124191, 2020). "In the thyroid, 16 of the SBGs were previously reported as cancer drivers, with 11 being over-expressed in females’ normal thyroid, including the oncogenes CARD11, EZH2, and IL7R." (PMID 32849808, 2020). "The epigenetic proteins EZH2 and KDM6B, two enzymes controlling the methylation level of the histone H3 at the position K27 (H3K27), are major components of cancer aggressiveness and EMT." (PMID 33291363, 2020). "EZH2 regulated aerobic glycolysis through miR-181b/hexokinase 2 (HK2) axis and played a positive role in cancer development." (PMID 32723346, 2020). "Two histone methyltransferases, enhancer of zeste homolog 2 (EZH2) and nuclear SET domain-containing 2 (NSD2), are aberrantly expressed in several types of human cancers." (PMID 33665162, 2020). "EZH2, a member of polycomb repressive complex 2 (PRC2), is commonly involved in transcriptional repression in cancer cells." (PMID 33763107, 2020). "EZH2 knockdown and EZH2 inhibitor treatment are reported to impair proliferation and colony formation in SWI/SNF-mutant cancer cells." (PMID 32906688, 2020). "EZH2, the catalytic subunit of PRC2, mediates the trimethylation of histone H3K27, epigenetically repressing target genes in human cancers." (PMID 32885590, 2020). "The results showed that EZH2 and DLC1 were differentially expressed in patients of different ages, races, cancer stages, molecular subtypes and histologic subtypes." (PMID 32725802, 2020). "Enhancer of zeste homolog 2 (EZH2) activates Notch signaling, thereby expanding cancer stem cell populations." (PMID 33066509, 2020). "EZH2 has attracted the most attention as a KMT, and its inhibitors in reversing drug resistance in various cancers have been reported." (PMID 32859239, 2020). "SMAD Family Member 2 (SMAD2) and Enhancer of Zeste Homolog 2 (EZH2) are two important genes that play roles in the cell cycle transition and cancer proliferation." (PMID 33330073, 2020). "To investigate the clinical impact of EZH2 and CXCR4 on GBM cancer progression, we analyzed the relationship between their mRNA expression levels and GBM patient prognosis with GEPIA." (PMID 32635336, 2020). "Many studies have suggested that there is a positive correlation between the expression level of EZH2 and PVT1 in many types of cancer." (PMID 32117705, 2020). "Compared with the cancer clusters, HMGB3, EZH2 and ZNF76were identified as candidate transcription factors whose expressions were specifically regulated in the CSC cluster." (PMID 33162821, 2020). "Thus, EZH2 may be a promising target for cancer immunotherapy." (PMID 32117960, 2020). "The protein expression levels of EZH2 and NSD2 in benign lesions were significantly lower than that in cancers." (PMID 33665162, 2020). "In the context of cancer, there is chronic antigen stimulation where such phenotypes as SLEC and MPEC may no longer be applicable, making the comparison to acute pathogenic infection more complicated in defining the CD8+ T cell subpopulations affected by EZH2 inhibition." (PMID 33117406, 2020). "Drosophila zeste gene enhancer homologue 2 (EZH2), as a catalytic subunit of PRC2, is a commonly up‐regulated epigenetic factor in cancer." (PMID 32725802, 2020). "Enhancer of zeste homolog 2 (EZH2) is a histone lysine methyltransferase that is involved in many human diseases, most of which are types of cancer." (PMID 33207561, 2020). "In a large number of human cancers, including breast, prostate, and bladder tumors, PRC2 dysregulation is the result of EZH2 overexpression." (PMID 32650416, 2020).
cancer (continued). "Known cancer genes such as EGFR, EZH2, or CCDN2 were frequently affected by duplications and other known cancer genes such as CDKN2A, RB1, KLK2, or CD79A were frequently affected by deletions." (PMID 32604718, 2020). "EZH2, the catalytic component of PRC2, writes the suppressive chromatin marker H3K27me3 and is overexpressed in many cancers including MB from all four groups." (PMID 32923515, 2020). "Owing to the important roles of EZH2 and BMI1 in epigenetic regulation, they are often overexpressed in cancer cells and are required for self-renewal of stem cells." (PMID 33168810, 2020). "In this review, we will focus on the role of the dynamic expression EZH2 in shaping the epigenetic landscape of CD8+ T cell fate and function, with a particular emphasis on infection and cancer." (PMID 33117406, 2020). "Pharmacological inhibition of EZH2, the core enzymatic component of PRC2, has been illustrated to effectively kill various cancer cells." (PMID 32127003, 2020). "These miRs can downregulate EZH2 by interacting with its 3’UTR sequence, thus, dysregulation of these miRs can up-regulate the EZH2 expression driving cancer progression." (PMID 33003334, 2020). "The enhancer of zeste homolog 2 (EZH2) is one of the HMTs family members with catalytic activity, which can promote cancer development." (PMID 32859239, 2020). "In addition to the association of GOF mutations in EZH2 with oncogenesis, some studies have implicated the overexpression of this gene in cancer development despite an absence of mutations in the coding region, such as in multiple myeloma, prostate, breast, and endometrial cancers." (PMID 32182803, 2020). "EZH2 is capable of regulating immune cells, including T cells and macrophages, thus performing decisive roles in regulation of TME and cell invasion in cancer cells." (PMID 31855281, 2020). "EED or EZH1 and EZH2 inhibition restored expression of MHC I antigen processing genes and effective T cell-mediated immunity in MHC I low cancers." (PMID 32182803, 2020). "In detail, highest levels of EZH2 expression were found in the pooled group of high-grade serous (HGSOC) and endometrioid (HGEOC) cancers (P < 0.001)." (PMID 33230143, 2020). "A study showed that expression of both the histone mark H3K27me3 and enhancer of zeste homolog 2 (EZH2) was decreased in breast CAFs and promoted cancer invasion by overexpression of thrombospondin type 1." (PMID 30680600, 2019). "Enhancer of zeste homolog 2 (EZH2) is the catalytic subunit of PRC2 complex, expression of which is elevated in all cancers including breast cancer." (PMID 30760814, 2019). "EZH2 promotes proliferation of CRC cells, and its silencing by siRNA leads to reduced cancer cell survival." (PMID 31864341, 2019). "Here, we show that EZH2, LSD1, DNMT1, and HDAC1 form interactions themselves, meanwhile, they also interact with SMAD proteins and β-CATENIN in cancer cells." (PMID 31130994, 2019). "We confirmed that EZH2 knockdown reversed the oncogenic roles of LINC00978 in HCC, suggesting that EZH2 recruitment and epigenetic silencing of downstream genes is a novel mechanism for the roles of LINC00978 in cancer." (PMID 31582742, 2019). "Hence, there might be cancer-related EZH2 functions that are independent from H3K27 methylation." (PMID 31317325, 2019). "To corroborate the staining results regarding cancer stem-like features in GSCs, we found robust expression of MELK, EZH2, and NF-κB in GSCs sorted from GBM cell-line, U87 and primary human GBM tissues, compared with control cultures." (PMID 31380279, 2019).
cancer (continued). "This pattern of heterogeneity was similar when considering a broader list of pan-cancer driver genes, with private amplification events seen in ERBB3, RHEB, SOS1, SOS2, and EZH2." (PMID 30348992, 2019). "EZH2, JMJD3 and UTX have been extensively studied for their involvement in development, immune system, neurodegenerative disease, and cancer." (PMID 31285428, 2019). "By silencing the tumor inhibitory gene via EZH2 recruitment, DANCR manages to promote cancer progression." (PMID 31799189, 2019). "EZH2 is frequently overexpressed in a variety of cancer including HCC and targeting EZH2 has shown promising therapeutic effects in cancer." (PMID 31582742, 2019). "Taken together, due to its high affinity for HOTAIR, ADQ treatment efficiently blocked the HOTAIR/EZH2 interaction via the 36G46A binding site, thereby reversing HOTAIR-induced cancer progression and metastasis." (PMID 30764859, 2019). "In sum, our findings not only uncover a novel role of EZH2 in regulating MDSC development, but also suggest that to achieve better anticancer outcomes, pharmacological inhibition of EZH2 in cancer therapy should be used in combination with MDSC depletion." (PMID 31160593, 2019). "EZH2 is the catalytic subunit of PRC2, which has been shown to be dysregulated in various different cancer types, including ccRCC." (PMID 31481081, 2019). "EZH2, LSD1, DNMT1, and HDAC1 are co-expressed in many types of cancer cells, as well as in neural progenitor/stem cells." (PMID 31130994, 2019). "The histone methyltransferases DOT1L and EZH2, as well as the demethylase LSD1, are three promising histone methyltransferases and demethylases in clinical trials for cancer therapy." (PMID 31888761, 2019). "To further verify the regulation of FOXO1 expression by EZH2, we treated C4-2 and 22Rv1 cell lines with histone deacetylase (HDAC) inhibitor SAHA, an FDA approved drug for cancer treatment." (PMID 31410199, 2019). "EZH2 is the catalytic subunit of Polycomb Repressive Complex 2 (PRC2) which trimethylates H3K27, and is upregulated in multiple cancer types including CRC, where its expression level correlates with worse prognosis." (PMID 30926792, 2019). "On screening the top 200 linear model genes against cancer driver genes in the Cancer Gene Census, only four genes were found, namely BUB1B, CDKN2A, EZH2, and RECQL4." (PMID 31277598, 2019). "Beyond playing its role in a PCR2-dependent manner as a histone modifier, EZH2 also acts in a PCR2 and histone independent manner in cancer." (PMID 29556394, 2018). "The mRNA and protein expression of EZH2 and SMYD3 in cancer tissues and adjacent tissues were detected by RT-qPCR and Western blotting." (PMID 29089464, 2018). "EZH2 in particular has a role in transcriptional repression through H3K27 tri-methylation and is considered an attractive epigenetic target for cancer therapy." (PMID 29487714, 2018). "Various studies have documented ribavirin acting via several pathways in cancer cells, including the IMPDH, ERK/MAPK, eIF4E, and EZH2 pathways." (PMID 29487714, 2018). "We next selected two novel EZH2 inhibitors DZNep and GSK343 to investigate their anti-cancer effects in combination with Resminostat against HCC." (PMID 30035186, 2018). "Here we report that EZH2 and KDM6B are overexpressed in numerous cancers and involved in the aggressive phenotype and EMT in various cell lines by regulating a specific subset of genes." (PMID 34991274, 2018). "EZH2, another member of the PRC2 complex, is over-expressed in cancer, enhancing cell growth and transformation." (PMID 29401683, 2018). "EZH2 also promoted EMT and cancer aggressiveness via the repression of genes involved in different signaling pathways." (PMID 34991274, 2018). "The results showed that the mRNA and protein expression of EZH2 and SMYD3 in cancer tissues were higher than those in adjacent tissues (P<0.05)." (PMID 29089464, 2018).